APOL1 (apolipoprotein L1)
Diseases named in the same sentence as APOL1 in open-access papers (continued):
Sharing a sentence is not in itself a finding about the gene and the disease.
sleeping sickness (continued). "Association studies examining APOL1 G1 and G2 have often grouped the two variants together as recessively ‘high-risk’, however for some conditions the different genotypes have distinct phenotypes for African sleeping sickness." (PMID 38360481, 2024). "This interaction prevents APOL1 insertion into endosomal membranes, allowing T. b. rhodesiense to escape from APOL1 lytic activity and consecutive parasite infectivity in humans, thereby causing sleeping sickness in east Africa." (PMID 39768205, 2024). "APOL1 kills Trypanosoma brucei through induction of apoptotic-like parasite death, but two T. brucei clones acquired resistance to APOL1, allowing them to cause sleeping sickness." (PMID 39451256, 2024). "Another example identified from studying admixed populations is kidney disease due to APOL1 variants which may have risen to high frequency in parts of Africa to provide protection against African sleeping sickness." (PMID 35842778, 2022). "APOL1 mutations are correlated with the distribution of sleeping sickness." (PMID 35308512, 2022). "The common human APOL1 variant G0 provides protection against infection with certain Trypanosoma and Leishmania parasite species, but it cannot protect against the trypanosomes responsible for human African trypanosomiasis." (PMID 34331942, 2021). "In contrast to Trypanosoma brucei gambiense and T. b. rhodesiense (the causative agents of human African trypanosomiasis), T. b. brucei is lysed by apolipoprotein-L1 (apoL1)-containing human serum trypanolytic factors (TLF), rendering it non-infectious to humans." (PMID 29346416, 2018). "Two variants of APOL1 termed G1 and G2 play a protective role against the African trypanosomes Trypanosoma brucei rhodensiense and Trypanosoma brucei gambiense, parasites that cause the most deadly form of sleep sickness in humans." (PMID 30557319, 2018). "Despite their close genetic proximity APOL1 G1 and G2 polymorphisms confer very different, and even opposing, dominant associations with human African trypanosomiasis susceptibility, yet appear convergent in their deleterious recessive contribution to kidney pathology." (PMID 28537557, 2017). "The human-infective trypanosomes, Trypanosoma brucei rhodesiense in East Africa and T. b. gambiense in West Africa have separately evolved mechanisms that allow them to resist APOL1-mediated lysis and cause human African trypanosomiasis, or sleeping sickness, in man." (PMID 27494254, 2016). "However, taken together with alleles of APOL1, there is an overall significant undertransmission of putative protective alleles to human African trypanosomiasis-affected children." (PMID 24005574, 2014). "Accordingly, the secreted APOL1 isoform was found responsible for innate human resistance to infection by the prototype African trypanosome Trypanosoma brucei brucei, which causes sleeping sickness, a lethal inflammatory parasitic disease widespread in the sub-Saharan part of the continent." (PMID 39451256, 2024). "In this study we present a novel APOL1 variant from a species of West African baboon that killed examples of all T. brucei sub-species, including T. b. rhodesiense, T. b. gambiense group 2, and T. b. gambiense group 1, the agent of most current cases of human African trypanosomiasis." (PMID 27494254, 2016). "Genes such as HBB and APOL1 have also been reported to have been subject to recent positive selection in Africa by conferring protection against infectious diseases such as Malaria and Trypanosomiasis (sleeping sickness), and APOL1 alleles have also been linked to cardiovascular disease." (PMID 27149122, 2016). "In the prevailing hypothesis, heterozygous APOL1 G1 and G2 alleles increase resistance against Trypanosoma that cause African sleeping sickness, resulting in positive selection of these alleles, but when homozygous the G1 and G2 alleles predispose to glomerulosclerosis." (PMID 23300552, 2012).
sleeping sickness (continued). "APOL1 forms an ion channel: in human African trypanosomiasis, APOL1 forms pores in parasite membranes, disrupting ionic balance, and causing lysis." (PMID 38360481, 2024). "APOL1 confers resistance to Trypanosoma brucei rhodesiense, the etiologic agent for African sleeping sickness." (PMID 35308512, 2022). "rhodesiense evades lysis by expressing serum resistance associated (SRA) protein that binds to the C-terminus domain of the APOL1, in the process neutralising its lytic activity leading to infection of the host and the development of African sleeping sickness." (PMID 34440683, 2021). "Apolipoprotein L1 (APOL1) is a minor component of plasma circulating High-Density Lipoprotein (HDL) capable to kill Trypanosoma brucei responsible for African sleeping sickness." (PMID 32915357, 2020). "Apolipoprotein L1 (APOL1) is a human innate immune factor against African trypanosomes responsible for human African trypanosomiasis (or sleeping sickness)." (PMID 30733721, 2019). "APOL1 was identified as a protective factor in human sleeping sickness, common in Sub-Saharan Africa, and it has been shown that only variants in APOL1 linked with renal dysfunction confer protection from disease." (PMID 30359254, 2018). "Apolipoprotein 1 (APOL1) is a component of both high-density lipoprotein (HDL) and the innate immune system; with regard to the latter, it functions as a protective factor against human African trypanosomiasis (HAT), which causes African sleeping sickness." (PMID 36217118, 2022). "The discovery that apolipoprotein L1 (APOL1) is the trypanolytic factor of human serum raised interest about the function of APOLs, especially following the unexpected finding that in addition to their protective action against sleeping sickness, APOL1 C‐terminal variants also cause kidney disease." (PMID 32530132, 2021). "The APOL1 sequences from theseindividuals have not been assessed, although a recent study assessing APOL1selection across Africa has identified an allele termed G3 that is under selectionin the Fulani people of Cameroon, a region affected by T. b.gambiense African sleeping sickness." (PMID 25656360, 2015).
diabetes (39 papers, 2011 to 2026). "An increased risk of CKD has been identified in African-American and Caribbean populations, in association with higher blood pressure, highly prevalent diabetes, and the presence of genetic variants of apolipoprotein L1 (APOL1)." (PMID 37953925, 2023). "As such, we calculated the fraction of DME risk in patients with diabetes that is attributable to the APOL1 locus." (PMID 37585454, 2023). "Main risk factors are family history of renal disease, genetic predisposition (such as Apoliprotein (APOL)-1 renal risk variants), immune suppression, history of proteinuria, diabetes, hepatitis C virus co-infection, and treatment with certain antiretroviral drugs." (PMID 30418933, 2018). "Similarly, genome-wide linkage analysis has revealed genetic variants on chromosome 22, near the MYH9 and APOL1 to be linked to the pathogenesis of diabetes." (PMID 23285077, 2012). "We defined T2D-ESKD candidate loci as genes which have been implicated in ESKD (diabetes associated or non-diabetes associated) either through direct (e.g. CNDP1, APOL1) genetic analysis or through compelling functional relationships (e.g. REN)." (PMID 24551085, 2014). "JUSTICE is a single-center, randomized, double-blind, placebo-controlled, pilot phase 2 trial of baricitinib in patients with proteinuria, APOL1-associated FSGS or APOL1-associated HTN-CKD without diabetes." (PMID 39291185, 2024). "Additional adjustment for comorbidities, specifically BMI, systolic blood pressure, diabetes, cardiovascular disease, smoking, alcohol use, and APOL1 genotype had only a mild impact (Model 2), and additional adjustment for proteinuria (Model 3) had a moderate impact on the strength of associations." (PMID 36048534, 2022). "In multivariable analysis, SCT (adjusted odds ratio 1.62 [95% CI 1.14–2.32]) and APOL1 high-risk genotypes (4.88 [3.57–6.67]) as well as age, prior AIDS, recent CD4 cell count, diabetes, and cardiovascular disease remained associated with eGFR <60 ml/min per 1.73 m2." (PMID 35257059, 2022). "Further information on APOL1/MYH9 variants may lead to screening programs which could lead to earlier detection and interventions for non-diabetic kidney disease." (PMID 22956460, 2013). "This increased allele frequency at the APOL1 locus resulted in an estimated 5% population attributable fraction of DME in non-Hispanic black patients with diabetes, over two times that of non-Hispanic white patients, despite the similar effect size for the SNP in each super-population." (PMID 37585454, 2023). "After adjustment for classical diabetes risk factors, glucose parameters (FPG, HbA1C), and plasma TG, we ultimately identified 4 apolipoproteins amongst 16 that remain significantly associated with new-onset T2D in individuals with prediabetes: apoE, apoF, apoJ, and apoL1." (PMID 35130909, 2022). "Black adults aged 18-70 years without diabetes or dialysis dependence underwent APOL1 genotyping and kidney disease screening." (PMID 41774497, 2026). "We observed a significantly higher protein expression of APOL1 by 12.8-fold in islets from three donors with (pre-)diabetes, while APOL2 and APOL6 were not significantly altered in these donors." (PMID 37924378, 2024). "West African ancestry and demographic factors were no longer associated with ESKD after adjustment for APOL1 status, whereas low CD4 cell count, diabetes, and cardiovascular disease remained associated with ESKD." (PMID 35497797, 2022). "Further, findings from previous studies of APOL1-by-SNP interaction were not significant among participants without diabetes in the present study." (PMID 36250097, 2022). "MYH9 rs3752462 (T>C) and APOL1 rs136161 (C>G) were genotyped in 303 DKD patients and 364 type 2 diabetes mellitus (T2DM) patients without kidney disease using the TaqMan SNP genotyping assay." (PMID 29862302, 2018).
glomerular disease (37 papers, 2012 to 2025). "In this case, the patient with SLE presented CG possibly caused by parvovirus B19 infection associated with homozygous apolipoprotein 1 (APOL1) G1 genotype, which has been described as a determinant risk factor for this glomerulopathy." (PMID 39792859, 2025). "Foamy macrophages were also seen in the glomeruli of individuals with high-risk APOL1 genotype and collapsing glomerulopathy." (PMID 40501951, 2025). "Previously established second-hit triggers of glomerulopathies in high-risk APOL1 variants include HIV, SLE, and IFN therapy." (PMID 40552181, 2025). "Prematurity was significantly more common in children and adults with APOL1 high-risk genotypes, typically with a glomerular disease diagnosis, lower eGFR at study entry, and faster eGFR decline compared to an APOL1 low-risk genotype." (PMID 40940784, 2025). "Individuals with primary FSGS or other primary glomerular diseases caused by or associated with high APOL1 risk genotype account for a very small fraction (<10%) of people of recent African ancestry with APOL1-associated kidney disease." (PMID 39680444, 2025). "Several examples in which high IFN states caused collapsing glomerulopathy in carriers of a high-risk APOL1 genotype led to a paradigm that pointed to IFNs as the chief “second-hit” triggers of APOL1-mediated glomerulopathy." (PMID 35472001, 2022). "Data from the NEPTUNE study of glomerular disease supports a role for APOL1 variants in enhancing inflammatory signaling." (PMID 32854642, 2020). "Data from the NEPTUNE study of glomerular disease patients indicated a role for APOL1 variants in enhancing glomerular expression of CXCL9 and CXCL11, chemokines induced by proinflammatory cytokines such as TNF and IL-1." (PMID 32854642, 2020). "Our case, therefore, not only allowed the identification of SM infection as an additional trigger for the development of CG but, also, strengthened the concept that a high-risk APOL1 genotype exerts a susceptibility role in this glomerulopathy." (PMID 33119586, 2020). "This agrees with the observation that APOL1 gene variants are associated with glomerular disease, which tends to manifest in a more rapid progression to end-stage kidney disease." (PMID 32854642, 2020). "APOL1 gene variants, present in individuals of recent sub-Saharan African descent, increase risk for glomerular disease and associate with the disease progression, but the molecular mechanisms have not been defined." (PMID 32854642, 2020). "Genetic variants in APOL1, encoding apolipoprotein L1, constitute a major cause of glomerular disease in individuals with sub-Saharan African ancestry." (PMID 30998685, 2019). "Despite these limitations, the association of HR APOL1 genotype with development of glomerular disease, later onset of FSGS and indications of increased cardiovascular risk among children were compelling." (PMID 27900314, 2016). "In the CKiD population, HR APOL1 risk genotype was strongly associated with both glomerular disease and FSGS." (PMID 27900314, 2016). "Factors associated with African ancestry in Brazil may explain the higher prevalence of APOL1 risk alleles in our population and, therefore, the higher incidence of severe glomerulopathies affecting young patients, such as CG." (PMID 41397399, 2025). "This hypothesis was supported by recent reports that transgenic overexpression of APOL1 risk alleles in mouse podocytes or GECs caused podocytopathy, endotheliopathy, glomerulopathy, and clinical manifestations of kidney failure." (PMID 35472001, 2022). "This may explain in part why glomerular disease is the most notable manifestation of APOL1 risk variants." (PMID 30417125, 2018). "Future studies to investigate the role of the different APOL1 variants and their role in podocyte cholesterol homeostasis under physiological and disease conditions are needed to shed light on their contribution to the pathogenesis of glomerular diseases." (PMID 25352833, 2014).
glomerular disease (continued). "There have been reported cases of IgG4-related kidney disease with concurrent glomerular diseases, such as membranous nephropathy, but this is the first reported case of IgG4-related kidney disease with concurrent FSGS associated with an APOL1 gene variant." (PMID 40264599, 2025). "In the Columbia-GN cohort, we identified 39 (3.6%) individuals with a monogenic glomerular disorder, mainly in patients with FSGS (35 individuals), along with 66 individuals (6.0%) with high-risk APOL1 genotypes." (PMID 39225089, 2024). "Interaction between miR-193a and apolipoprotein 1 (APOL1) mRNA in glomeruli (filtration units of kidneys) is potentially involved in the pathogenesis of common glomerular diseases." (PMID 38136614, 2023). "Glomerular disease is associated with an APOL1 sequence variant, which encodes apolipoprotein L1, expressed in podocytes, and an important component of HDL." (PMID 35782060, 2022). "While the incidence of advanced kidney disease due to HIVAN has decreased with the use of ART, HIVAN remains a valuable model for the study of podocyte injury and APOL1-induced glomerular disease." (PMID 34722586, 2021). "For comparison, there is the known linkage of the risk of collapsing glomerulopathy including HIV-associated nephropathy (HIVAN) in African patients who have G1 and G2 polymorphisms of the APOL1 gene, which are protective against trypanosomal disease." (PMID 33868143, 2021). "In this report, we describe a patient with a high-risk APOL1 genotype (HRG) who developed CG in the setting of SM, raising this helminth infection as a likely additional trigger for this severe form of glomerulopathy." (PMID 33119586, 2020). "Of those 28 subjects with HR APOL1 status and a glomerular disease, 25/28 (89%) had a diagnosis of FSGS." (PMID 27900314, 2016). "We further showed that this approach is suitable for screening for mutations in selected genes that are associated with glomerular disorders in patients suspected to have AS or FSGS clinically, or detection of G1 or G2 APOL1 variants in African Americans." (PMID 24130771, 2013). "Recent reports of new glomerular disease in individuals with APOL1 high-risk genotype (HRG) following SARS-CoV-2 vaccination raised the concern SARS-CoV-2 vaccination may also act as a second-hit driver of APOL1-mediated glomerulopathy." (PMID 39291186, 2024). "Notably, a series of 29 cases of biopsy-proven glomerular disease in patients recently vaccinated against SARS-CoV-2 identified 2 occurrences of collapsing glomerulopathy in African American/Black individuals with APOL1 HRG." (PMID 39291186, 2024). "To date, there are no studies about the impact of APOL1 HRG on the risk of SARS-CoV-2 vaccine-associated glomerular disease." (PMID 39291186, 2024). "HIVAN has a predilection for African populations and has been linked with high-risk variants of the APOL1 gene (i.e., G1 and G2), which have been associated with several nondiabetic glomerular disorders including HIVAN." (PMID 35743539, 2022). "Glomerular disease presenting as proteinuria with or without AKI was also considered as an important presentation of COVID-19 infection in patients with a high-risk APOL1 genotype." (PMID 34541999, 2021). "Since the vast majority of HR children in CKiD had a glomerular disease (85%), we were unable to assess the effect of APOL1 HR on cardiovascular risk among those with a non-glomerular condition." (PMID 27900314, 2016). "While efforts are underway to screen patients for G1 and G2 alleles and to better understand “APOL1 glomerulopathy,” no data prove that these APOL1 sequence variants cause glomerulosclerosis." (PMID 23300552, 2012). "However, genome-wide analyses have found associations between MYH9 SNPs and glomerular disease independent of APOL1." (PMID 24949636, 2014). "For individuals with APOL1 HRG, conditions that increase cytokines can result in podocytopathy, glomerular disease, and proteinuria." (PMID 39291186, 2024).
glomerular disease (continued). "Likewise, it is possible that decreased podocyte APOL1 expression under disease conditions leads to decreased cholesterol efflux from podocytes and cellular cholesterol accumulation, thus contributing to the pathogenesis of glomerular diseases such as FSGS and HIVAN." (PMID 25352833, 2014). "Because our cohort did not include individuals with APOL1 HRG with known preexisting glomerular disease, the generalizability of our results to these individuals is uncertain." (PMID 39291186, 2024). "The lack of association between APOL1 HRG and new-onset glomerular disease in the present study follows a recent retrospective cohort study that evaluated risk of any glomerular disease relapse after SARS-CoV-2 vaccination." (PMID 39291186, 2024). "The highest diagnostic yield for monogenic glomerular disorders (8.7%) and high-risk APOL1 genotypes (19%) was observed in patients with FSGS, as expected given the rarity of monogenic forms of non-FSGS glomerulopathies." (PMID 39225089, 2024). "While this is an initial caveat of all discoveries from genome wide association studies due to linkage, such caution is not currently stressed amidst the momentum of APOL1-glomerulopathy." (PMID 23300552, 2012).